SLC7A5 (solute carrier family 7 member 5)
Diseases named in the same sentence as SLC7A5 in open-access papers (continued):
Sharing a sentence is not in itself a finding about the gene and the disease.
lung carcinoma (27 papers, 2008 to 2026). "Here, we demonstrated that inhibition of tryptophan uptake by knockdown of SLC7A5 in the lung cancer cell caused subsequent decrease of cellular level of NAD, along with attenuation of glycolytic activity." (PMID 37095081, 2023). "Studies indicate that SLC7A5 shows significantly elevated expression in various malignant tumors, including GC, colon cancer, lung cancer, and prostate cancer, especially has been shown to be a promoter of GC." (PMID 40133832, 2025). "We demonstrated that IGF2BP2 promotes lung cancer radioresistance by forming a positive feedback loop with SLC7A5 to activate the AKT/mTOR pathway." (PMID 38281999, 2024). "In lung carcinomas, increased SLC7A5 expression contributes to an immunosuppressive tumor microenvironment and reduces the efficacy of immunotherapeutic treatments." (PMID 38256136, 2024). "Clonogenic survival assays, neutral comet assays, Rad51 foci formation assays, and Annexin V/propidium iodide assays were used to determine the significance of FBW7/IGF2BP2/SLC7A5 axis in lung cancer radioresistance." (PMID 38281999, 2024). "Specifically, the FBW7/GSK3β/IGF2BP2/SLC7A5 axis was characterized and shown to play a vital role in lung cancer radiosensitivity." (PMID 38281999, 2024). "Overall, our study explicitly identified a positive feedback loop involving the m6A “reader” IGF2BP2 and the amino acid transporter SLC7A5 in lung cancer radioresistance." (PMID 38281999, 2024). "Thereafter, the TCGA, CPTAC, and ENCORI databases exhibit the high expression of SLC7A5 in lung cancer tissues." (PMID 38987867, 2024). "This provides a deeper understanding of c-Myb's regulation on SLC7A5 expression in lung cancer cells." (PMID 37692503, 2024). "The interaction of HMMR with SLC7A11 activates ferroptosis, enhances the cytotoxic effect of CD8 +T cells, and regulates the tumor immune microenvironment, suggesting an interaction with SLC7A5 in lung cancer." (PMID 39228892, 2024). "We demonstrated that this positive feedback loop between IGF2BP2 and SLC7A5 promotes lung cancer radioresistance through the AKT/mTOR pathway." (PMID 38281999, 2024). "Other studies have reported that several lncRNAs sponge miR-126 in lung cancer cells and increase SLC7A5 expression." (PMID 36499136, 2022). "Long ncRNA plasmacytoma variant translocation 1–5 has been shown to act as a sponge for miR-126 in lung cancer cell lines, which prevents miR-126 from regulating SLC7A5." (PMID 35755805, 2022). "MiR-126 has been identified as a direct regulator of SLC7A5 in both gastric and lung cancer, while miR-126 is downregulated in gastric cancer and can function as a tumor suppressor." (PMID 35755805, 2022). "Apart from the findings in lung cancer, a recent report showed that triggering naïve T cells via antigen receptors increases SLC7A5 expression and bioavailability of Met and results in increased levels of H3K4me3 and H3K27me3 in vitro and in vivo." (PMID 33401748, 2021). "Expression of SLC7A5 has been detected in a variety of tumor cells, including thyroid cancer, teratocarcinoma, bladder cancer, lung cancer, melanoma, hemangiopericytoma, and uterine cervical cancer." (PMID 26244545, 2015). "Similarly, IGF2BP2 promotes lung cancer radio-resistance by forming a positive feedback loop with SLC7A5, enhancing its stability and translation through m6A modification." (PMID 41522349, 2026). "We assessed whether genetic deletion of SLC7A5 in T cells affect GVT response using a BALB/c compatible murine lung carcinoma cell line, KLN-205, injected in the flank of recipient mice (Fig. EV5)." (PMID 40399490, 2025). "This evidence shows that TRIM29 is a link between EGFR and SLC7A5 in lung cancer cells." (PMID 37692503, 2024). "HBV may also attach to members of the solute carrier family, such as SLC7A5, another common overregulated gene in lung cancer." (PMID 39228892, 2024).
lung carcinoma (continued). "Collectively, our study revealed that the m6A “reader” IGF2BP2 promotes lung cancer radioresistance by forming a positive feedback loop with SLC7A5, suggesting that IGF2BP2 may be a potential therapeutic target to control radioresistance in lung cancer." (PMID 38281999, 2024). "Solute carrier family 3 member 2 (SLC3A2), or CD98hc, encodes another subunit of heterodimeric amino acid transporter that is overregulated in six lung cancer datasets and establishes a heterodimeric transmembrane protein complex with SLC7A5 to catalyze amino acid transport." (PMID 39228892, 2024). "The overexpression of PVT1 could upregulate expression levels of SLC7A5 mRNA and induce the proliferation of lung cancer cells by acting as a sponge for miR-126." (PMID 36499136, 2022). "SLC7A5 expression was found to be associated with significantly lower 5-year survival rates in SLC7A5-positive lung cancer patients than in SLC7A5-negative ones, which might be associated with tumor proliferation, angiogenesis, and a poor prognosis." (PMID 36499136, 2022). "Nutrient transporter SLC2A1 and SLC7A5 both exhibit cancer-promoting potential in lung cancer." (PMID 33129284, 2020). "However, little is known about the role of SLC7A5 in lung cancer radioresistance." (PMID 38281999, 2024). "Hence, we surmised that the FBW7/GSK3β/IGF2BP2/SLC7A5 axis may modulate lung cancer radiosensitivity." (PMID 38281999, 2024). "Elevated OCTN1 and OCTN2 mRNA levels are reported in human lung carcinoma, while LAT1 (SLC7A5) is upregulated in NSCLC." (PMID 38534987, 2024). "Using an in vivo lung cancer metastasis model, we established orthotropic breast tumor-bearing BALB/c mice by inoculating 4T1 cells into the fat pad to investigate the role of SLC7A5 in cancer metastasis." (PMID 37731509, 2023). "Gene knockdown experiments revealed a critical role of SLC7A5 for the transport of Met and maintenance of the intracellular SAM levels in lung cancer." (PMID 33401748, 2021). "The protein SLC7A5 is part of a two‐protein complex with SLC3A2 and the gene was hypermethylated and its expression increased in lung cancer." (PMID 30761256, 2019). "Taken together, our study delineated a previously unknown mechanism of a positive feedback loop between IGF2BP2 and SLC7A5, and highlighted the role of the FBW7/GSK3β/IGF2BP2/SLC7A5 axis in radioresistance in lung cancer." (PMID 38281999, 2024). "LAT1 (SLC7A5) is the main BCAA transporter, which belongs to the Na+- and pH-independent L-type amino acid transporters (system L/antiporter) SLC7 family and is highly expressed in many cancers, including the most frequently diagnosed cancers, such as lung cancer, prostate cancer, and breast cancer." (PMID 33511116, 2020). "Since SLC7A5 has been widely reported to activate the AKT/mTOR pathway, and the AKT/mTOR pathway has been found to regulate reactive oxygen species and protect cells from DNA damage, we speculated that the IGF2BP2-SLC7A5 loop may confer radioresistance on lung cancer through the AKT/mTOR pathway." (PMID 38281999, 2024).
colorectal cancer (21 papers, 2016 to 2025). A primary or metastatic malignant neoplasm that affects the colon or rectum. "Co-expression analyses of the TCGA and CPTAC colorectal cancer cohorts identified a network of gene transcripts positively related to SLC7A5, with its heterodimer partner SLC3A2 having the highest co-expression score." (PMID 38722983, 2024). "Together with data from TCGA and CPTA, our study also identified a SLC7A5 co-expression network that links SLC7A5 function to ncRNA processing and cell cycle in colorectal cancer." (PMID 38722983, 2024). "Correlation of SLC7A5 protein expression with clinicopathological features of colorectal cancer patients." (PMID 38722983, 2024). "In this study, we investigated the expression of an essential amino acid transporter SLC7A5 (solute carrier family 7 member 5) in colorectal cancer tissue and for its prognostic potential in early-stage disease." (PMID 38722983, 2024). "In a third cohort of 210 colorectal cancer cases, SLC7A5 high expression was observed in 72.4% of the patients but no prognostic conclusion was given." (PMID 38722983, 2024). "In summary, using large well-annotated cohorts of colorectal cancer tissue, this study identified increased tissue protein expression of SLC7A5 to be a favorable prognostic marker in early-stage colorectal cancer." (PMID 38722983, 2024). "The results showed that only four genes, including ATP6V1F, PPP1R14B, BTF3L4 and SLC7A5, were oncogenes that are required for cell proliferation of stomach cancer, liver cancer and colorectal cancer." (PMID 36620589, 2022). "The gene expression correlation analysis showed that miR-194 expression showed a negative correlation with the expression of ATP6V1F, PPP1R14B, BTF3L4 and SLC7A5 in gastric cancer, liver cancer and colorectal cancer." (PMID 36620589, 2022). "Consistent with our results, ATP6V1F, PPP1R14B and SLC7A5 were reported to play oncogenic roles in colorectal cancer progression." (PMID 36620589, 2022). "SLC7A5 is essential for cell functions in numbers of carcinomas, and has been detected highly expressed in prostate cancer, ureteral cancer and colorectal cancer." (PMID 27846244, 2016). "To clarify and define the role of SLC7A5 expression in colorectal cancer, we investigated two well-annotated cohorts of 681 colorectal cancer patients, including 575 early-stage and 106 late-stage cancers, as well as the TCGA and CPTA colorectal cancer cohorts for complimentary insights." (PMID 38722983, 2024). "In KRAS-mutant colorectal cancer cells, SLC7A5 maintained intracellular amino acid level and activated mTOR pathway, which finally supported cell proliferation; in small cell lung cancer, increased SLC7A5 promoted cell growth." (PMID 38556586, 2024). "Overall, our study provides clear evidence of differential SLC7A5 expression and its prognostic value for early-stage colorectal cancer, although the understanding of its functions in colorectal tumorigenesis and cancer immunity is currently rather limited and awaits further characterization." (PMID 38722983, 2024). "In addition, a study has shown that the amino acid transporter SLC7A5 is essential for the effective growth of KRAS mutant colorectal cancer." (PMID 39588377, 2024). "Since SLC7A5 is also a marker of activated lymphocytes such as NK, T, and B lymphocytes, SLC7A5 overexpression in early colorectal cancers might trigger a strong anti-tumor immune response which could results in better clinical outcome." (PMID 38722983, 2024). "By analyzing the mRNA expression of SLC1A5, SLC3A2, and SLC7A5 in human colon cancer samples deposited in The Cancer Genome Atlas (TCGA) database (n = 41 matched pairs of normal and colorectal cancer samples), we found that all three genes had elevated expression in nearly all patients." (PMID 31416966, 2019). "In addition, in KRAS-mutant colorectal cancer, Slc7a5 disruption abrogates tumor cell growth." (PMID 38617535, 2024).
colorectal cancer (continued). "In this study, we examined the expression of an essential amino acid carrier SLC7A5 (LAT1, CD98, or 4F2 light chain) in cancer tissue from two well-annotated cohorts of 575 cases of early-stage and 106 cases of late-stage colorectal cancer patients." (PMID 38722983, 2024). "LINC00857 is upregulated and acts as an oncogene in colorectal cancer to promote colorectal cancer proliferation, migration and invasion by interacting with YTHDC1 and stabilizing SLC7A5." (PMID 35418193, 2022). "For instance, the inhibition of Glut2 (Slc2a2) dynamics has the potential to improve diabetes mellitus in mice, and Slc7A5, a glutamine antiporter, could be an attractive target for therapy-resistant, KRAS-mutant colorectal cancer in mice." (PMID 36787192, 2023). "Interestingly, YTHDC1 ultimately combined with solute carrier family 7 member 5 (SLC7A5) and increased SLC7A5 mRNA stability to promote the proliferation and migration of colorectal cancer cells, implicating the critical role of LINC00857/YTHDC1/SLC7A5 axis in colorectal cancer progression." (PMID 37365581, 2023).
gastric cancer (19 papers, 2013 to 2025). A primary or metastatic malignant neoplasm involving the stomach. "This stabilized circFAM192A subsequently drives gastric cancer cell proliferative capacity by inhibiting solute carrier family 7 member 5 (SLC7A5) mRNA turnover." (PMID 40986143, 2025). "CircARID1A acted as a scaffold to promote the interplay of IGF2BP3 and SLC7A5 mRNA, which ultimately increased the stability of SLC7A5 mRNA and thus promoted gastric cancer cell proliferation." (PMID 38577615, 2024). "While SLC7A5 is upregulated in gastric cancer cells, miR-126 directly targets SLC7A5 and miR-126 overexpression can inhibit cancer cell proliferation." (PMID 35755805, 2022). "Depletion of CRKL in a gastric cancer cell line resulted in impairment of SLC7A5 expression and suppression of cell motility." (PMID 33429909, 2021). "In summary, in this study, both CRKL and SLC7A5 were over-expressed in gastric cancer cell lines and tissues." (PMID 27846244, 2016). "The aim of this study is to investigate the regulating effect of CRKL, one of the critical genes involving with gastric cancer progression, on SLC7A5 expression." (PMID 27846244, 2016). "The findings in this study indicate a regulation relationship between CRKL and SLC7A5, and provide useful evidence for gastric cancer therapeutic strategies." (PMID 27846244, 2016). "Our previous research showed a clearly high expression of SLC7A5 in both gastric cancer tissues and cell lines." (PMID 27846244, 2016). "The findings here indicate a regulating relationship between CRKL and SLC7A5, and provide further evidence to advance new targets for gastric cancer therapeutic treatment." (PMID 27846244, 2016). "By knocking down SLC7A5 in gastric cancer SGC-7901 cells, the cell proliferation was impaired along with a significant arrest of G0/G1 phase of cell cycle." (PMID 27846244, 2016). "Results above, combining with what we observed in tumor cells and tissues, strongly illustrate a positive correlation between CRKL and SLC7A5 in gastric cancer cells." (PMID 27846244, 2016). "By studying the gastric cancer cell lines and clinical pathological specimens, we found that the expression of SLC7A5 was significantly correlated to CRKL." (PMID 27846244, 2016). "Furthermore, we found that SLC7A5 is closely related to immune infiltration analysis and CNV mutation, with significant differences in these two functions among gastric cancer patients with different SLC7A5 expressions." (PMID 40133832, 2025). "Therefore, our study demonstrated that FTO promoted gastric cancer proliferation through the circFAM192A/SLC7A5 axis in the m6A-dependent manner." (PMID 38556586, 2024). "In contrast, ectopic expression of SLC7A5 is in favor of gastric cancer metastasis and invasion." (PMID 38705513, 2024). "It was found that CRKL depletion impaired gastric cancer progression via SLC7A5 downregulation." (PMID 38705513, 2024). "In the present study, we modulated the expression of CRKL in SGC-7901 cells, and observed that the depletion of CRKL in gastric cancer SGC-7901 cells was companied with a down-regulation of SLC7A5 at both mRNA stage and protein stage, which suggests SLC7A5 as a downstream gene of CRKL." (PMID 27846244, 2016). "However, the mechanisms driving SLC7A5 to affect the bio-function of gastric cancer cells are unclear, remaining us lots of to elucidate." (PMID 27846244, 2016). "Thus, SLC7A5 functions as a promoter in gastric cancer metastasis, and CRKL could be one of its regulators modulating its expression and consequentially affects the metastatic feature of SGC-7901 cells." (PMID 27846244, 2016). "In gastric cancer, GSE1 promotes tumor progression via SLC7A5-mediated enhancement of growth and metastasis, and contributes to trastuzumab resistance." (PMID 41208974, 2025). "By depleting CRKL in gastric cancer SGC-7901 cells, the SLC7A5 expression was impaired, and the invasion and migration of SGC-7901 cells were suppressed." (PMID 27846244, 2016).
gastric cancer (continued). "Accordingly, we conclude that SLC7A5 functions as a promoter in gastric cancer metastasis, and CRKL could be one of its regulators modulating the expression of SLC7A5 and consequentially affect the metastatic feature of SGC-7901 cells." (PMID 27846244, 2016). "Additionally, downregulation of SLC7A5 by shRNAs inhibited growth of prostate and gastric cancer cells, but did not affect proliferation of cholangiocarcinoma cells or ovarian cancer cells." (PMID 30241549, 2018).